TNFAIP8 (TNF alpha induced protein 8)
Diseases named in the same sentence as TNFAIP8 in open-access papers (continued):
Sharing a sentence is not in itself a finding about the gene and the disease.
tumor (continued). "Tumors with TNFAIP8 overexpression tended to display more aggressive phenotypes, including larger tumor size (p=0.0056), advanced TNM stage (p=0.0180) and higher recurrence rate (p=0.0038)." (PMID 28152516, 2017). "We further showed that TNFAIP8 upregulated cell proliferation, migration, invasion and xenograft tumor growth of HCC cells." (PMID 28152516, 2017). "TNFAIP8 also correlated with poor overall survival in HCC subgroups with single tumor and tumor size >5cm." (PMID 28152516, 2017). "The rates of tumor growth of TNFAIP8 depleted Bel7402 and HepG2 were decreased compared with control." (PMID 28152516, 2017). "In order to investigate the functions of TNFAIP8 in tumor formation, the present study inhibited its function via siRNA treatment in the MKN-28 and SGC-7901 cell lines, which exhibit higher expression levels of TNFAIP8." (PMID 25936980, 2015). "TNFAIP8 has an important regulatory role in cell apoptosis and signal transduction, as well as tumor occurrence, development and invasion." (PMID 26063084, 2015). "In the present study, the protein levels of TNFAIP8 were examined using IHC staining in normal tissues and tumor tissues, varying in depth of invasion." (PMID 25936980, 2015). "Internalized TNFAIP8 recruits the E3 ligase TRIM21 to facilitate STAT1 ubiquitination and degradation, leading to the induction of myofibroblastic CAF-associated features, accompanied by enhanced extracellular matrix deposition and tumor growth." (PMID 41709860, 2026). "This highlights a functional divergence between TNFAIP8L3 in the OVCA setting and its homologs in other cancer types, where TNFAIP8 may act more directly in tumor cell survival and proliferation." (PMID 40343258, 2025). "High expression of TNFAIP8 has been shown to promote tumor growth and migration." (PMID 40343258, 2025). "Furthermore, SPON1 and TNFAIP8 have demonstrated context-dependent effects, with implications in both tumor promotion and inhibition." (PMID 39858632, 2025). "TIPE (TNFAIP8) has been identified as an oncogene and participates in tumor biology." (PMID 39728923, 2024). "TNFAIP8 correlated positively with high M2-like CD163-positive tumor-associated macrophages (TAMs) and non-GCB cell of origin phenotype." (PMID 36358737, 2022). "In addition, according to the data from GEPIA2, TNFAIP8 expression was upregulated in DLBCL tumor (n = 47, p < 0.05), similar to that of TIPE1." (PMID 36118167, 2022). "However, in TCGA data, different from most other tumor types, the low expression level of TNFAIP8 in SKCM relative to adjacent tissues attracted our attention." (PMID 34925463, 2021). "It has been shown that TNFAIP8 plays important roles in the formation and development of tumours, while being involved in the regulation of cell proliferation, tumour invasion, migration, death and drug resistance in different tumour types." (PMID 33682317, 2021). "In addition, the expression levels of EFNA1 (P = 2.68E−02), TNFAIP8 (P = 2.77E−02), and TNFAIP8L3 (P = 6.48E−03) showed a significant association with tumour stage." (PMID 34344926, 2021). "Furthermore, we explored the correlation between the TNFAIP8 expression and immune infiltration immune cell–related markers in the tumor microenvironment by bioinformatics tools." (PMID 34925463, 2021). "Subsequently, we demonstrated high expression of TNFAIP8 in clinical ccRCC samples and tumor cells." (PMID 32226521, 2020). "Furthermore, we found that TNFAIP8 rs1045242 polymorphism had an effect on clinical significance of FIGO stage, residual tumor, and recurrence, indicating its progressive role in OC." (PMID 32821249, 2020).
tumor (continued). "Although overexpression of TNFAIP8 in a variety of tumor cell lines enhances tumor proliferation and migration 10, it is unknown that TNFAIP8 exerts clinically meaningful effects and related mechanisms in RCC, particularly in ccRCC." (PMID 32226521, 2020). "TNFAIP8 plays a role in immune homeostasis, inflammatory responses, tumor genesis, and development." (PMID 32318089, 2020). "Notably, tumor lymph angiogenesis was also significantly repressed after lncRNA H19 or TNFAIP8 knockdown." (PMID 32514245, 2020). "In addition, TNFAIP8 rs1045242 gene polymorphism was linked to advanced FIGO stage, larger residual tumor, and the presence of recurrence in OCs." (PMID 32821249, 2020). "Tumor necrosis factor-α-induced protein 8 (TNFAIP8) expression has been linked to tumor progression in various cancer types, but the detailed mechanisms of TNFAIP8 are not fully elucidated." (PMID 32152268, 2020). "Pathological staining analysis of the lymph node samples using HE staining and TNFAIP8 IHC staining also revealed that suppression of lncRNA H19 reduced significantly vacuole and necrosis lesions in lymph node tissues induced by tumor cells, as well as the expression level of TNFAIP8 protein." (PMID 32514245, 2020). "Because autophagy plays an important role in both tumor development and cancer cell survival, we investigated whether TNFAIP8 is involved in cellular autophagy via dysregulation of cell-cycle-related proteins." (PMID 29928491, 2018). "TNFAIP8 is critical for tumour proliferation and chemoresistance in tumours." (PMID 30064446, 2018). "TNFAIP8 was mainly localized to the cytoplasmic compartment of tumour cells." (PMID 30064446, 2018). "TNFAIP8 shRNAs reduced in vitro cancer cell proliferation and in vivo tumor growth." (PMID 30064446, 2018). "Moreover, TNFAIP8 overexpression was correlated with platinum resistance in epithelial ovarian cancer and residual tumor size." (PMID 29108244, 2017). "Furthermore, the expression of TNFAIP8 in the tumor tissues was higher than in the adjacent normal tissues." (PMID 25936980, 2015). "As for TNF-αsignaling pathway, experimentally demonstrates that knock-down of the TNFα-induced protein TNFAIP8 in tumor cells decreases their oncogenicity, which suggests TNFAIP8 may be involved in carcinogenesis." (PMID 26718335, 2015). "Knocking down the expression of TNFAIP8 in tumor cells can reduce their tumorigenicity." (PMID 25946186, 2015). "The results provide further evidence that, in addition to enhancing tumorigenesis in other types of tumor, TNFAIP8 may be involved in promoting cell proliferation, invasion and migration." (PMID 25936980, 2015). "In addition, TNFAIP8 also played a significant role in drug resistance of tumor cells." (PMID 34901263, 2021). "Finally, we explored the molecular effect of lncRNA and TNFAIP8 inhibition on tumor growth in vivo." (PMID 32514245, 2020). "Of these genes, TNFAIP8, TIPE1, and TIPE3 are known to greatly influence tumor occurrence and development, while TIPE2 is mainly involved in innate immunity and acquired immunity." (PMID 36118167, 2022). "Previous studies have shown that interventional chemotherapy can promote tumor cell apoptosis; inhibit tumor growth, invasion, and metastasis; and improve prognosis by regulating the expressions of VEGF, Caspase-9, TNFAIP8, and Prdx4." (PMID 36476481, 2022). "As the tumour stage progressed, the expression of EFNA1 increased, while that of TNFAIP8 and TNFAIP8L3 decreased." (PMID 34344926, 2021).
tumor (continued). "TNFAIP8 and FOCAD candidate genes are known to play a role in immune homeostasis and tumor suppression." (PMID 31379916, 2019). "Using immunohistochemistry, western blot and realtime PCR, we showed that TNFAIP8 was significantly upregulated in human HCC tissues, which correlated with larger tumor size, advanced TNM stage and recurrence, decreased overall and disease-free survival." (PMID 28152516, 2017). "Univariate analysis revealed that tumor size, recurrence, TNM stage and TNFAIP8 expression were statistically correlated with patients' survival." (PMID 28152516, 2017). "TNFAIP8, also termed NDED, GG2-1, SCCS2, SCC-S2 and MDC-3.13, is located in 5q23.1 and is involved in the malignancies of numerous types of tumor." (PMID 25936980, 2015). "In orthotopic models, TNFAIP8 silencing or lipid nanoparticle-mediated shTNFAIP8 delivery reduced fibrosis, suppressed tumor progression, and enhanced gemcitabine efficacy without evident toxicity, suggesting the feasibility of a therapeutic approach." (PMID 41709860, 2026). "BAD promotes cell death, and TNFSF14 protein stimulates the proliferation of T cells and trigger apoptosis of tumor cells—while TNFAIP8 acts as the negative mediator of apoptosis." (PMID 36839713, 2023). "This body of research shows that TNFAIP8 and TIPE3 may act as oncogenes, while TIPE2 is likely a tumor suppressor gene." (PMID 36118167, 2022). "The role of TNFAIP8 in tumor aggression was apparent in the negative control groups, compared with the TNFAIP8-siRNA treatment group (P<0.01)." (PMID 25936980, 2015). "Furthermore, in the Cox analysis of TNFAIP8 using the tumor immune estimation resource (TIMER), we found that higher TNFAIP8 expressions were also dramatically consistent with the optimistic OS in both SKCM and SKCM metastasis patients (p = 0.002 and p < 0.001)." (PMID 34925463, 2021).
cancer (25 papers, 2012 to 2025). A tumor composed of atypical neoplastic, often pleomorphic cells that invade other tissues. "Our results agree with those of previous studies, which indicate that TNFAIP8 is associated with platinum resistance in advanced cancer." (PMID 30064446, 2018). "TNFAIP8 has been implicated as an oncogenic molecule that regulates cancer cell progression in various human cancers." (PMID 29928491, 2018). "Members of the TNFAIP8 gene family have been linked to regulation of immune function and homeostasis and the development of multiple cancer types." (PMID 28658311, 2017). "Although the TNFAIP8 gene family has been associated with inflammation, immunity, and cancer, little is known about the mechanisms by which these genes function and the evolutionary origins of the family are not yet fully understood." (PMID 28658311, 2017). "The TNFAIP8 and TNFAIP8L2 genes participate in immunity and inflammation, while all members of the TNFAIP8 gene family have been associated with cancers of various types, including those affecting the stomach, liver, prostate, lung, esophagus, and cervix." (PMID 28658311, 2017). "The TNFAIP8 expression is elevated in a variety of cancer tumors, and a higher expression is associated with a lower survival rate of patients, suggesting that TNFAIP8 may play an important role in tumorigenesis as an oncogene." (PMID 34925463, 2021). "Polymorphisms of TNFAIP8 gene are reported to be associated with risks of different cancers." (PMID 32821249, 2020). "In cancer cells, expression of TNFAIP8 is associated with cell survival and drug resistance." (PMID 32152268, 2020). "In addition, our study indicated that the TNFAIP8 rs1045242 polymorphism had a meaningful joint effect with no smoking history and pre-menopausal on strengthening the risk of cancer." (PMID 31043860, 2019). "Since miR-483 inhibits cell survival and migration, we also analyzed the effect of miR-483 on the expression of Nanog and CD44 cancer stem cell markers and oncogenic TNFα-Induced Protein 8 (TNFAIP8) marker." (PMID 36980601, 2023). "The cancer group had higher TNFAIP8 serum (Wilcoxon, p < 0.001) and IL-6 levels (Wilcoxon, p < 0.001) when compared with the control group." (PMID 37296861, 2023). "The control group presented higher expression levels of SCFA and FFAR2, while the cancer group had higher levels of TNFAIP8, IL6, and STAT3." (PMID 37893122, 2023). "Several studies have reported that TNFAIP8 is induced by NF-κB1, inhibits cellular apoptosis, acts as an oncogene, and promotes cell growth/proliferation in human cancers." (PMID 34134766, 2021). "Although the role of TNFAIP8 in negative regulation of apoptosis in malignancies have been well documented, the mechanisms by which TNFAIP8 functions vary among different cancer types and cell contexts." (PMID 32795319, 2020). "Overexpression of TNFAIP8 is frequently observed in malignant tumors, that is significantly correlated to excessive proliferation, reduced apoptosis, enhanced invasion and metastasis, and drug resistance." (PMID 32821249, 2020). "The study of TNFAIP8 in cancer cells has established some basic features of TNFAIP8 biology, but how these processes differ in other cells, such as immune cells has not been fully established." (PMID 31723944, 2019). "Recently, we and others have analyzed the detailed molecular roles of TNFAI8 in human cancer, providing a starting point for investigation the role of TNFAIP8 in other conditions." (PMID 31723944, 2019). "SNP rs11064, rs1045241, and rs1045242 in TNFAIP8 were successfully genotyped in 248 cancer-free controls and 226 ECs by SNaPshot method, respectively." (PMID 31043860, 2019).
cancer (continued). "Collectively, these results clearly showed that TNFAIP8 isoforms expression is highly variable between different cancer cell lines." (PMID 29928491, 2018). "TNFAIP8 contains a death effector domain, which negatively regulates apoptosis in several types of cancer." (PMID 29928491, 2018). "RT-PCR and immunoblotting data suggested that other TNFAIP8 isoforms are also expressed in various cancer cell lines." (PMID 29928491, 2018). "Several isoforms of TNFAIP8 have been identified which are involved in various physiological processes and diseases, including cancer." (PMID 29928491, 2018). "Ectopic expression of TNFAIP8 in cancer cells imparts resistance to TNF-α-induced apoptosis, which was associated with increased autophagy." (PMID 29928491, 2018). "TNFAIP8 overexpression in cancer cells is induced by TNF-α and NF-κB activation in various cells; these actions enhance cell survival and proliferation by inhibiting apoptotic protein caspase-8 and caspase-3 activity." (PMID 30064446, 2018). "The biological significance of TNFAIP8 protein in the regulation of cancer biology is reported in the literature with limited studies." (PMID 30586922, 2018). "TNFAIP8 expression increases significantly in various cancer cell lines, leading to cancer progression and poor prognosis." (PMID 29928491, 2018). "TNFAIP8 is induced by NF-kB, inhibits cellular apoptosis, acts as an oncogenic molecule, and promotes cell growth/proliferation in human cancers." (PMID 29928491, 2018). "Several studies showed that TNFAIP8 plays a role in the cellular anti-apoptotic process and promotes cellular growth and proliferation in various cancers." (PMID 29928491, 2018). "In human cancers, TNFAIP8 promotes cell proliferation, invasion, metastasis, drug resistance, autophagy, and tumorigenesis by inhibition of cell apoptosis." (PMID 30586922, 2018). "In cancer tissues, cases with high TNFAIP8 protein expression tended to show strong YAP nuclear staining and low p-LATS1." (PMID 28152516, 2017). "TNFAIP8 is also overexpressed in cervical, ovarian, prostate, gastric carcinoma and promotes cancer cell growth and invasion." (PMID 28152516, 2017). "Our results support a model that LATS1 is responsible for TNFAIP8 induced change of cancer cell growth and Hippo signaling, which is further supported by the fact of TNFAIP8/LATS1 interaction." (PMID 28152516, 2017). "TNFAIP8 is also aberrantly expressed in various human cancer cell lines, with higher levels in K562 chronic myelogenous leukemia cells, MOLT 4 lymphoblastic leukemia cells and A549 lung carcinoma and lower levels in SW480 colorectal adenocarcinoma cells." (PMID 24137373, 2013). "Evidence showed that TNFAIP8 expression was upregulated by TNF-α induced NF-κB pathway activation in cancer cell lines, which can inhibit caspase-8 and reduce apoptosis." (PMID 22666399, 2012). "For instance, TNFAIP8, a closely related protein, has been found to be highly expressed in various malignancies such as breast, prostate, and lung cancers." (PMID 40343258, 2025). "This reduction may contribute to the promotion of TNFAIP8 and IL-6/STAT3, ultimately provoking inflammation and potentially increasing the risk of developing cancer." (PMID 37296861, 2023). "We have confirmed that alterations in the composition of oral bacteria can contribute to a reduction in SCFAs and the expression of the FFAR 2, resulting in an inflammatory response through the upregulation of TNFAIP8 and the IL-6/STAT3 pathway, ultimately increasing the risk of cancer onset." (PMID 37296861, 2023). "By inhibiting cell apoptosis, TNFAIP8 promotes cancer cell proliferation and drug resistance." (PMID 32152268, 2020). "In patients with no smoking history and no family cancer history, the GG allele of TNFAIP8 rs11064 SNPs played a protective factor for OC." (PMID 32821249, 2020).